RAP1GAP (RAP1 GTPase activating protein)
Diseases named in the same sentence as RAP1GAP in open-access papers (continued):
Sharing a sentence is not in itself a finding about the gene and the disease.
Papillary Thyroid Carcinoma (1 paper, 2021). "Rap1GAP is considered a tumor suppressor gene, but its regulatory mechanism in papillary thyroid cancer (PTC) has not been clearly elucidated." (PMID 34840979, 2021).
renal carcinoma (1 paper, 2020). A carcinoma arising from the epithelium of the renal parenchyma or the renal pelvis. "Of these, several genes including CASP5, RAP1GAP, and GREM1 have been reported to be involved in the pathogenesis of renal cancer or significant in predicting overall survival, suggesting that the present analysis using the TCGA database has potential prognostic value." (PMID 32952743, 2020).
Thrombocytopenia (1 paper, 2017). A reduction in the number of circulating thrombocytes. "We furthermore show that two Rasa3 mutants (H794L and G125V), which are expressed in different mouse models of thrombocytopenia, lack both Ras and Rap1GAP activity and do not affect integrin αIIbβ3-mediated spreading of CHO cells on fibrinogen." (PMID 27903653, 2017).
tumor (22 papers, 2012 to 2025). "The lower level of Rap1GAP is thought to be associated with the size of the tumor, the advanced tumor-node-metastasis, and indicates a worse prognosis." (PMID 34952616, 2021). "Other studies have also shown that the depletion of Rap1GAP in breast cancer led to reduction in E-cadherin levels as well as ERK activation that is associated with enhanced tumor invasiveness." (PMID 32906721, 2020). "The downregulation of Rap1GAP was frequently associated in tumor cell lines which underwent epithelial-to-mesenchymal transition (EMT)." (PMID 32906721, 2020). "Rap1GAP is likely to serve as an important tumor suppressor in GC, and its loss during carcinogenesis contributes to tumor progression and metastasis." (PMID 28009991, 2017). "Additionally, a re-expression of Rap1GAP was associated with a reduction in tumor size." (PMID 32906721, 2020). "In tumor cells, miRNAs such as miR-149 and miR-101 regulate Rap1 directly or through its negative regulator Rap1GAP." (PMID 40508181, 2025). "Upon further literature review, we found that TIAM1 and RAP1GAP have already been reported as an oncogene and a tumor suppressor gene, respectively, in TC, with their roles validated through cellular biology experiments 35-37." (PMID 40092686, 2025). "In an independent investigation, Kim and his research group found that diminishing Rap1GAP levels in tumor cells amplifies their aggressiveness within the context of CRC32." (PMID 37945594, 2023). "Cd274 and Zbtb32 negatively regulate immunity, and S100a4, Rap1gap, Armc3, and Prkar2b promote tumor metastasis, This was consistent with the emergence of immunosuppression in the later stages of E. granulosus infection and with the hydatid cyst metastasis." (PMID 36569953, 2022). "Our findings that n-butyrate inhibited endometriotic cell growth, in part, via RAP1GAP are consistent with the role of RAP1GAP as a tumor suppressor in multiple cancers." (PMID 34593556, 2021). "Rap1GAP, an important tumor suppressor, impedes the invasion and migration of cancer cell through the downregulation of Rap1." (PMID 32528886, 2020). "In some instances, Rap1GAP expression is further downregulated in cancers, suggesting that its depletion contributes to tumor progression." (PMID 32906721, 2020). "In contrast, restoring Rap1GAP expression in tumor cells not only inhibits invasion and migration, but also inhibits anchorage-dependent proliferation." (PMID 32906721, 2020). "Collectively, these results suggest that the downregulation of Rap1GAP contributes to aggressive phenotypes of tumor, reduces E-cadherin expression, and increases expression of EMT features." (PMID 32906721, 2020). "Low expression of Rap1GAP was positively correlated with advanced pTNM stage, Borrmann types, tumor diameter and poor prognosis in patients with GC." (PMID 28009991, 2017). "Thereafter, overexpression of Rap1GAP in cancer cells impairs cell migration and invasion in vitro, and inhibits tumor formation and metastasis in vivo." (PMID 28009991, 2017). "Although Rap1GAP was detected in the tumor cells, there was a marked decrease in the staining intensity in these cells compared to the para-carcinoma tissues." (PMID 28009991, 2017). "Only have few studies have investigated the role of Rap1GAP in promoting the invasion of tumor cells via the upregulation of MMP9 secretion." (PMID 28009991, 2017). "In this study, we found that Rap1GAP expression in cancer tissues was lower than adjacent non-tumor tissues." (PMID 28009991, 2017). "In the present study, we found significant correlations between low Rap1GAP expression and the pTNM stage, nodal involvement, metastasis, Borrmann types, tumor diameter and poor overall survival." (PMID 28009991, 2017). "In human colon carcinoma cells, downregulation of Rap1GAP promotes tumor progression by altering cell/matrix and cell/cell adhesion." (PMID 28009991, 2017).
tumor (continued). "The low expression level of Rap1GAP was closely correlated with the pTNM stage, nodal involvement, metastasis, Borrmann types, tumor diameter and poor overall survival." (PMID 28009991, 2017). "The alterations in cell/cell and cell/matrix adhesion are early steps in tumor metastasis supports a role for Rap1GAP depletion in tumor progression." (PMID 28009991, 2017). "Although Rap1GAP is recognized as a tumor suppressor gene and downregulated in various cancers, little is known regarding the regulation of Rap1GAP ubiquitination and degradation under physiological conditions." (PMID 25329897, 2014). "Rap1GAP is a tumor suppressor gene and downregulated in various cancers such as squamous cell carcinoma, renal cell carcinoma, melanoma, pancreatic cancer, and thyroid cancer." (PMID 25329897, 2014). "We found that β1 integrin activation in tumor cells and hepatic colonization was reduced by overexpression of the Rap1GAP tumor suppressor." (PMID 23056350, 2012). "Overexpression in tumor cells of the tumor suppressor, Rap1GAP, inhibited Rap1 and β1 integrin activation as well as hepatic colonization." (PMID 23056350, 2012). "Rap1GAP was also identified as a tumor suppressor in pancreatic cancer." (PMID 41303422, 2025). "Inactivation of Rap1 by Rap1GAP resulted in strong tumor inhibition." (PMID 41303422, 2025). "Additionally, the oncogene EZH2 upregulates the downregulation of miRNA‐101, which in turn downregulates rap1GAP, another tumor suppressor gene, encouraging head and neck malignancies." (PMID 38522008, 2024). "It has been reported that the expression of Rap1GAP is abundant in well-differentiated rat thyroid cells, but it is selectively reduced in tumor cell lines with mesenchymal morphology, and restoration of Rap1GAP expression can inhibit tumor cell migration and invasion." (PMID 34840979, 2021). "Given the role of RAP1GAP as a tumor suppressor and our data indicating that its expression is up-regulated by n-butyrate, we wondered whether RAP1GAP is required for n-butyrate–mediated suppression of cellular viability." (PMID 34593556, 2021). "Inhibition of Rap1 activity with its negative regulator, Rap1GAP, impairs tumor progression." (PMID 32906721, 2020). "However, while constitutively-active β1 integrin L358A rescued the suppressive effect of over-expressed Rap1GAP on tumor cell extravasation, it was less able to rescue the suppressive effect of Rap1GAP on hepatic colonization." (PMID 23056350, 2012). "Therefore, we hypothesized that low expression of Rap1GAP in PTC cells may promote tumor invasion by altering cell-cell and cell-matrix adhesion." (PMID 34840979, 2021). "Interestingly, Rap1 and Rap1GAP demonstrated contrasting effects on a tumor." (PMID 32906721, 2020). "Hence, Rap1GAP played an important role in the migration and invasion capacity of tumor cells." (PMID 28009991, 2017). "Thus, Rap1GAP may also exert a β1 integrin activation-independent effect on tumor cell colonization after extravasation has occurred (for example on tumor cell survival, proliferation or apoptosis)." (PMID 23056350, 2012). "The downregulation of Rap1GAP expression can activate the TGF-β/Smad3 pathway to inhibit NIS expression and alter the tumor cell functions of PTC." (PMID 34840979, 2021). "Its tumor invasiveness was blocked by MMP inhibitor, suggesting that Rap1GAP inhibits proliferation but enhances the invasive potential of SCC via MMP secretion." (PMID 32906721, 2020). "Multiple tumor suppressors were expressed at lower levels in EBVaGCs including five (TFF2, RBP4, HOXA9, LRRN1, and RAP1GAP) that are known to be hypermethylated in cancers." (PMID 23671415, 2013). "While the tumor-suppressive roles of TIAM1 and RAP1GAP have been previously established, our findings reveal that the overexpression of GPX3 and JUN significantly impairs the proliferative and migratory capacities of TC cells, underscoring their potential as therapeutic targets." (PMID 40092686, 2025).
tumor (continued). "This suggests that TIAM1 may function as an oncogene, while RAP1GAP, JUN, and GPX3 might act as tumor suppressors." (PMID 40092686, 2025). "Further results of ChIP assays revealed that SNHG22 could recruit EZH2 to the promoter regions of multiple tumor suppressor genes (E-cadherin, EAF2, ADRB2, rap1GAP and RUNX3), and modulating H3K27me3 levels to repress their transcription." (PMID 34663788, 2021). "Low-expression of Rap1GAP was closely correlated with the pTNM stage, nodal involvement, metastasis, Borrmann types and tumor diameter, but not to the patients’ age, gender, the depth of invasion and histology." (PMID 28009991, 2017). "Little is known about Rap1GAP and MMP2 in GC, and here we addressed a significant correlation between Rap1GAP and MMP2, simultaneously, our results showed that overexpression of Rap1GAP suppressed the expression of MMP2 and the migration and invasion capacity of tumor cells." (PMID 28009991, 2017). "Thus, a role for β1 integrin activation may explain, in part, recent experimental work demonstrating the effects on tumor progression of manipulating the expression of Rap1, the Rap1 effector, RIAM, Rap1GAP and talin." (PMID 23056350, 2012). "Interestingly, some of them function as tumor suppressors (e.g. BCL2L11, MXD1, WWOX, BNIP3L, and DMTF1) or are candidate tumor suppressors having anti-proliferative properties and DNA repair abilities (e.g. LRRC2, RPA4, PPP6R1, SPEN, RAP1GAP and CISH) (see discussion section)." (PMID 26918450, 2016).
cancer (21 papers, 2008 to 2025). A tumor composed of atypical neoplastic, often pleomorphic cells that invade other tissues. "It encodes for Rap1Gap protein that inactivates Rap, which is a protein involved in cancer growth, invasion, and metastasis." (PMID 26198328, 2015). "Several previous studies have reported that increased Rap1-GTP regulated by its negative regulator Rap1GAP can impair the progression of cancers." (PMID 38448739, 2024). "Rap1GAP, a negative regulator of Rap1, is downregulated in various cancer types, leading to increased aggressiveness and acquisition of EMT markers." (PMID 38891880, 2024). "It is found that Rap1GAP was down-regulated in many cancers, such as breast cancer, squamous cell carcinoma, pancreatic cancer, renal cell carcinoma, thyroid cancer, gastric cancer, and colorectal cancer." (PMID 34952616, 2021). "Rap1GAP is a family member of GTPase-activating proteins and is believed to be involved in cancer progression." (PMID 34840979, 2021). "The expression of Rap1GAP was determined in formalin-fixed, paraffin-embedded cancer tissues and para-carcinoma tissues by immunohistochemistry." (PMID 28009991, 2017). "Restoring Rap1GAP expression to these cancer cells inhibited cell proliferation, migration, and invasion, effects that were correlated with the inhibition of Rap1 activity." (PMID 25329897, 2014). "Deletion of Rap1GAP, in fact, prevents the formation of adherens junctions between carcinoma cells." (PMID 35054818, 2022). "Furthermore, Rap1GAP has also been identified as a more effective cell-matrix inhibitor, and overexpression of Rap1GAP in cancer cells can impair cell proliferation and migration on type IV collagen." (PMID 34840979, 2021). "Rap1GAP, a tumor suppressor gene, is down-regulated in many cancers." (PMID 34952616, 2021). "Very little is known about the definitive role of Rap1GAP in cancers." (PMID 32906721, 2020). "The molecular mechanism of Rap1GAP down-regulation in cancers is poorly understood." (PMID 28009991, 2017). "Therefore, the downregulation of Rap1GAP expression is correlated with a poor prognosis in cancer." (PMID 32906721, 2020). "Rap1GAP could be a promising therapeutic target in combating cancer." (PMID 32906721, 2020). "Therefore, Rap1GAP could serve as a therapeutic target in cancer therapy." (PMID 32906721, 2020). "Treatment with decitabine restoring the expression of Rap1GAP showed a significant reduction in the invasiveness of SN12C and Caki1 of matrigel matrices, suggesting a role in cancer cell invasion." (PMID 26198328, 2015). "Furthermore, increased Rap1GAP expression reduces EMT progression, invasion, and migration in various cancer types." (PMID 38891880, 2024). "As such, Rap1GAP and Rap1 may act as potential prognostic markers and novel targets of EMT and metastasis in cancers." (PMID 32906721, 2020). "However, Rap1Gap was shown to have no impact on cancer cell proliferation in either of the two cell lines." (PMID 26198328, 2015).
cardiovascular diseases (1 paper, 2021). "Here, we demonstrate that Rap1GAP induces cardiomyocyte apoptosis which might be a main mechanism of Rap1GAP in cardiovascular diseases." (PMID 33936386, 2021). "However, our ongoing experiment of mass spectrometry analysis might be able to reveal more significant signaling pathways that are involved in the functional roles of Rap1GAP in cardiovascular diseases." (PMID 33936386, 2021).
infection (1 paper, 2021). The state of being infected such as from the introduction of a foreign agent such as serum, vaccine, antigenic substance or organism. "HPV16/18 infection likely triggers the degradation of Rap1GAP via UPP, which leads to the down-regulation of Rap1GAP in HPV16/18 infected cells." (PMID 34952616, 2021).
RAP1GAP also shares sentences with these, for which no sentence is quoted: autism (2 papers); diabetes (1); Encephalopathy (1); head and neck carcinoma (1); heart failure (1); Insulin resistance (1); kidney cancer (1); myeloid leukemia (1); neuroblastoma (1); non-alcoholic fatty liver disease (1); prostate carcinoma (1); psoriasis (1).